IGF2BP2 (insulin like growth factor 2 mRNA binding protein 2)
Diseases named in the same sentence as IGF2BP2 in open-access papers (continued):
Sharing a sentence is not in itself a finding about the gene and the disease.
cancer (continued). "In colorectal cancer (CRC), IGF2BP2 maintains RAF1 mRNA stability by blocking miRNA-mediated degradation, thereby increasing cancer cell proliferation." (PMID 32911345, 2020). "For example, we found that IGF2BP2, which is closely related to GBM and LGG, can be closely related to the mesenchymal transition (EMT) pathway of cancer progression." (PMID 33323543, 2020). "As evidence has shown important roles of IGF2BP1, IGF2BP2, and IGF2BP3 in cancer, we next explored their expression in various types of cancer." (PMID 33575259, 2020). "Poor survival rates in patients were associated with the increased expression of these genes across cancer types, such as IGF2BP1 (HR = 1.324527, P = 2.38E-06) in LUAD and IGF2BP2 (HR = 1.198617, P = 0.006603) and IGF2BP3 (HR = 1.570331, P = 0.000198) in LIHC." (PMID 33519919, 2020). "IGF2BP2 mediates stabilization of HMGA1 mRNA and production of IGF2 which synergistically drive cancer progression." (PMID 31852504, 2019). "The IGF2 mRNA binding protein family (IGF2BPs) is comprised of three members: IGF2BP1, IGF2BP2, and IGF2BP3, which are bona fide oncofetal proteins involved in various human cancers." (PMID 26547929, 2015). "Yisraeli (2005) had suggested that the VICKZ family, to which IGF2BP2/IMP2 belongs, have a role to play in cell polarity and migration, cell proliferation and cancer." (PMID 19832977, 2009). "However, abnormal expression of IGF2BP2 and reactivation of IGF2BP1 and IGF2BP3 are frequently observed during cancer progression." (PMID 41049442, 2025). "Furthermore, IGF2BP2 expression positively correlated with LUCAT1, HMGA1 and cancer stem cell markers expression in BC cells." (PMID 40025525, 2025). "Our subgrouping analysis based on 25 m6A-associated genes revealed distinct m6A regulation-driven subgroups in six cancers, with IGF2BP family members (IGF2BP1, IGF2BP2, IGF2BP3; all known m6A readers) emerging as a central factor distinguishing these subgroups." (PMID 41049442, 2025). "Here, we demonstrate that elevated IGF2BP2 expression is predominantly confined to cancer cells, rather than dysplastic epithelial cells, suggesting its potential utility as a diagnostic biomarker for OSCC." (PMID 40362183, 2025). "Collectively, these findings unveiled a previously unrecognised role for IGF2BP2 in regulating ferroptosis sensitivity and immune microenvironment remodelling in CRC, expanding our understanding of its multifaceted functions in cancer malignancy through both m6A‐dependent and independent mechanisms." (PMID 41399129, 2025). "Consistent with this idea, the viability of PLK1-overexpressing cancer cells in the absence of IGF2BP2 activity was partially rescued by supplying exogenous ATP in our experiments." (PMID 40347943, 2025). "Recently, IGF2BP2 was shown to promote CRC progression by stabilizing oncogenic mRNAs, including YAP mRNA, a downstream nuclear effector of the Hippo signaling pathway with a role in the development and progression of multiple cancers." (PMID 40022181, 2025). "This review focuses on RBPs, particularly HuR, NONO, IGF2BP2 and 3, Musashi1 and 2, Lin28, RBM, Pumilio, YTHDF1, and AUF1, which are most extensively studied in association with cancer drug resistance." (PMID 38328550, 2024). "Targeting IGF2BP2 and TFRC may represent innovative approaches for the diagnosis and treatment of cancer." (PMID 38602575, 2024). "We observed that changes in IGF2BP2 levels did not affect cancer cell cycle progression but consistently altered the migration and invasion responses in OSCC cells." (PMID 38250159, 2024). "Remarkably, IGF2BP2 regulates glutamine uptake and metabolism by upregulating MYC, glutamic–pyruvic transaminase 2 (GPT2), and solute carrier family 1 member 5 (SLC1A5) in AML, demonstrating that IGF2BP2s can influence amino acid metabolism in cancer." (PMID 39596216, 2024).
cancer (continued). "Exercise-induced higher levels of miR-150 in circulating EVPs may repress IGF2BP2 and ZEB1 expression in target tissues, which may mediate the effects of exercise on some cancer types." (PMID 36936170, 2023). "Though several substrates of IGF2BP1 and IGF2BP3 are known in cancers, including ESCC, the downstream mRNAs regulated by IGF2BP2 are largely unknown." (PMID 37444412, 2023). "Mechanistically, IGF2BP2 is identified to be SUMOylated at the lysine residues K497, K505, and K509 by small ubiquitin-related modifier 1 (SUMO1), promoting the progression of cancer." (PMID 37554271, 2023). "In the present study, it was shown that IGF2BP2 was highly expressed in HNSCC tissues with lymphatic metastasis compared with those without lymphatic metastasis, implying a potential role of IGF2BP2 in promoting lymphatic metastasis in cancers." (PMID 34980207, 2022). "In addition, the Oncomine database was used to verify the high expression of IGF2BP2 and IGF2BP3 in cancer tissues." (PMID 36686749, 2022). "The connections between positive IGF2BP2 protein expression and lymph node metastases, as well as between IGF2BP2 and AJCC cancer stage, suggest that IGF2BP2 may play a role in OSCC metastasis." (PMID 35919812, 2022). "Besides lncRNAs, circCD44 also directly interacts with IGF2BP2 to enhance the stability of c-MYC mRNA in m6A-modifed manner, promoting cancer progression in triple-negative breast cancer." (PMID 35541906, 2022). "IGF2BP2 and IGF2BP3, members of the mammalian IGF2 mRNA-binding protein family, were found correlated with an overall poor prognosis and metastasis of various cancer." (PMID 34332578, 2021). "Consequently, LINRIS knockdown weakens downstream effects of IGF2BP2, particularly MYC-mediated glycolysis in CRC cells and proliferation of cancer cells." (PMID 33568150, 2021). "In addition, the oncogene lncRNA LINC00460 combines with IGF2BP2 and upregulates the expression of HMGA1 mRNA and increase its stability, participating in cancer development." (PMID 35004679, 2021). "In our study, m6A-seq and RNA-seq revealed that FEN1 was the downstream gene of IGF2BP2 and confirmed the oncogenic effect of FEN1 and revealed an m6A-dependent regulatory mechanism to partially explain the common upregulation of FEN1 in cancer." (PMID 33224879, 2020). "In our work, we think that MYC can be regulated by both METTL3/IGF2BP2 axis and SOX2 respectively, which might partially explain the elevated expression of MYC in various human cancers." (PMID 31230592, 2019). "In turn, a high level of IGF2BP2 enhances the expression of IGF2 which activates the PI3K/Akt/mTOR pathway and promotes the proliferation, migration, and epithelial-mesenchymal transition of cancer cells." (PMID 29736175, 2018). "Levels of HMGA1, HMGA2, PLAGL2, IGF2BP2, E2F5, and ARID3A transcripts were also inversely proportional to levels of Let-7 miRNA by examination of a cohort of 199 CRC patients from the TCGA Pan-Cancer analysis project." (PMID 26244988, 2015). "Immunohistochemical analysis of xenograft tumors revealed that IGF2BP2 knockdown promoted redifferentiation, as evidenced by a concomitant significant increase in the differentiation marker SLC5A5 (NIS) with a marked reduction in the cancer stem cell marker CD133, compared to shNC controls." (PMID 41522349, 2026). "Taken together, these studies suggest that IGF2BP2 inhibitors have high therapeutic potential and that with further refinement the application of these compounds would allow us to effectively reduce PLK1 protein levels and ultimately suppress PLK1-overexpressing cancer cells and tumors." (PMID 40347943, 2025). "In the HGSOC data set, the mtSNVs were called in most cancer and noncancer cells, and some fusion calls were expressed in most clones or subclones (P2: IGF2BP2::TESPA1, P1: SMG7::CH507-513H4.1, etc.), making them ideal variations for cell type reannotation and clustering." (PMID 40107722, 2025).
cancer (continued). "IGF2BP2, a m6A reader protein, is a member of the IGF2 mRNA‐binding protein family that regulates various post‐transcriptional processes such as mRNA localization, stability, and translation by recognizing the m6A modifications on transcripts critical for cancer initiation and progression." (PMID 39948708, 2025). "Remarkably, IGF2BP2 governs glutamine uptake and metabolism by upregulating MYC, glutamic-pyruvic transaminase 2 (GPT2), and solute carrier family 1 member 5 (SLC1A5) in AML, which indicates that IGF2BPs could regulate amino acid metabolism in cancers." (PMID 37554271, 2023). "However, whether IGF2BP2 regulates Slug expression via m6A modification and affects the process of EMT in cancer cells still needs to be elucidated." (PMID 34980207, 2022). "Insulin-like growth factor 2 mRNA-binding protein 2 (IGF2BP2) is a member of the conserved single-stranded RNA binding protein family IGF2, and is expressed in a wide range of fetal tissues, as well as in >16 types of cancer, but only in a limited number of normal adults’ tissues." (PMID 34608837, 2021). "In contrast, the suppression of cancer cell progression and glycolysis could be reversed by overexpressing IGF2BP2, especially by the K139R mutant without the LINRIS-binding site." (PMID 31791342, 2019). "Our finding that the HPV E6/E7/IGF2BP2/m6A-MYC/glycolysis axis may play a key role in the pathogenesis of CC suggests that targeting HPV E6/E7 and downstream pathways may represent an attractive therapeutic option for the treatment of patients with this cancer." (PMID 35002506, 2022). "The relationship between IGF2BP2 and 21 kinds of immune cells indicated a negative correlation between IGF2BP2 and B cells, CD4+ T cells, follicular helper T cells, regulatory T cells (Tregs), myeloid-derived suppressor cells, and cancer-associated fibroblast cells in HNSCC." (PMID 33816266, 2021). "For example, IGF2BP1 and IGF2BP2 have a shared consensus GG(m6A)C binding sequence, though in adult cancer cells, the binding of IGF2BP1 and not IGF2BP2 results in the protection of some oncogenic transcripts (e.g., SRF) from miRNA-directed transcript downregulation." (PMID 32707690, 2020). "Hence, CWI1-2, by targeting the endogenous IGF2BP2/EGFR/PI3K/AKT axis, represents a novel therapeutic approach that overcomes EGFR-targeted resistance attributed to both autonomous and non-cell-autonomous interactions between cancer cells and CAFs." (PMID 40362183, 2025). "For example, the specific molecular mechanism between HULC and IGF2BP2 is not clear; considering that HULC expression does not affect IGF2BP2 changes, we hypothesize that HULC may play a pro-cancer role by recruiting IGF2BP2 and thus, but this requires further studies to explore this mechanism." (PMID 39668820, 2024).
infection (7 papers, 2021 to 2025). The state of being infected such as from the introduction of a foreign agent such as serum, vaccine, antigenic substance or organism. "The red and green circles identify the partners of the STRING network whose association with IGF2BP2 is decreased and increased during infection, respectively." (PMID 39565347, 2024). "Subsequently, we upregulated the expression of IGF2BP2 in colon tissues of mouse models through infection of lentiviruses (P < .01)." (PMID 40241612, 2025). "At last, we reduced miR-222-3p expression in colon tissue samples through the lentiviruses infection (P < .01), after which the expression of IGF2BP2 and NCOA3 was increased in the colon tissues (P < .01)." (PMID 40241612, 2025). "IGF2BP2 mRNA expression increased in a dose‐dependent manner across multiplicities of infection (MOIs) of 25, 50, and 100, with an MOI of 100 selected for further experiments." (PMID 40485217, 2025). "To globally evaluate changes in the IGF2BP2 interactome upon infection, we analyzed the protein composition of IGF2BP2-HA complexes immunopurified from uninfected cells or infected with ZIKV or DENV by mass spectrometry (MS)." (PMID 39565347, 2024). "Additional experiments looking into HNRNPs and the interaction between HNRNPs and IGF2BP2 in EV-A71 infection should be carried out." (PMID 34511027, 2021). "To investigate the effects of the IGF2BP2 protein on the production of EV-A71, we designed two siRNAs against human cellular IGF2BP2 and checked the level of EV-A71 after 24 h of infection of KMB17 cells." (PMID 34511027, 2021). "Zika virus (ZIKV) infection alters the IGF2BP2 proteo-interactome." (PMID 39565347, 2024). "Intriguingly, ATL2/RBMX interaction was detected only in DENV-infected cells, suggesting that it is induced by the infection and might play a similar role as the one of IGF2BP2/ATL2 in case of DENV." (PMID 39565347, 2024). "We chose to focus on those mRNA because: (i) ZIKV, in addition to other Flaviviridae viruses (DENV, WNV, and HCV), alter their N6-adenosine methylation status during infection, and (ii) IGF2BP2 is a well-described ‘m6A reader’ which regulates the fate of bound RNAs." (PMID 39565347, 2024). "However, ATL2 was reported to regulate DENV replication even if it does not associate with IGF2BP2 in that infection context." (PMID 39565347, 2024). "IGF2BP2 expression remained unchanged at 2 and 3 dpi in contrast to DDX3 and DDX5 whose levels were decreased over the course of infection." (PMID 39565347, 2024). "The expression of Igf2bp2 was notably hindered in the livers of mice following the AAV8 administration, indicating a successful infection with AA8-shIgf2bp2." (PMID 38443347, 2024).
metabolic disease (7 papers, 2013 to 2024). A congenital disorder (due to inherited enzyme abnormality) or acquired (due to failure of a metabolically important organ) disorder resulting from an abnormal metabolic process. "More intriguingly, the association between IGF2BP2 SNPs and metabolic diseases varies even within the same ethnic population." (PMID 33568150, 2021). "The sections that follow discuss in detail, the associations between IGF2BP2 and several metabolic diseases." (PMID 33568150, 2021). "The association between IGF2BP2 and human metabolic diseases stems in its post-transcriptional regulation of numerous genes in different cell types and pathway." (PMID 33568150, 2021). "The role of IGF2BP2 in glucose tolerance, insulin sensitivity, fatty acid oxidation and the development of metabolic diseases had been reviewed recently." (PMID 33568150, 2021). "We demonstrate that polymorphisms genetically and structurally associated with human lncRAP2 are linked to metabolic diseases, but their impact on the expression or function of human lncRAP2/Igf2bp2 and their targets was not investigated." (PMID 35036870, 2022). "However, IGF2BP2 may induce human metabolic diseases via posttranscriptional regulation of various genes associated with specific cell types and pathways." (PMID 33568150, 2021).
adenocarcinoma (3 papers, 2015 to 2024). A common cancer characterized by the presence of malignant glandular cells. "Interestingly, the IGF2BP1, IGF2BP2, and HNRNPC genes displayed strong prognostic performance in adenocarcinoma, as validated in two independent cohorts of patients." (PMID 38539567, 2024).
cardiac disease (2 papers, 2023 to 2024). "Thus, the post-transcriptional mechanism underlying IGF2BP2 function in heart disease requires further investigation, and it will be interesting to examine whether modulating the expression or activity of IGF2BP2 could rescue cardiac dysfunction in DCM." (PMID 38535111, 2024). "Heart tissue from patients with various cardiac diseases was stained for IGF2BP2 protein." (PMID 38052926, 2023).
head and neck tumor (2 papers, 2023 to 2024). "This study suggested that m6A methylation regulators played an important role in head and neck tumor progression and demonstrates that IGF2BP2 and IGF2BP3 were prognostic indicators and potential biomarkers for immunotherapy in OSCC and OED." (PMID 36793593, 2023).
hematological malignancies (1 paper, 2021). "From the analysis on the “Total” data set IGF2BP1, ALKBH5, IGF2BP2, RBM15, METTL3, ZNF217 is the potentially carcinogenic gene in hematological malignancies." (PMID 33816257, 2021).
kidney disorder (1 paper, 2022). A disease involving the kidney. "The prediction of the enrichment of the RBPs associated with kidney disorders was laid out with IGF2BP2 and MSI1 in the hypermethylated group." (PMID 35795641, 2022). "Additionally, we also predated the enrichment of the RBPs associated with kidney disease including IGF2BP2 and MSI1 in the hypermethylated group." (PMID 35795641, 2022).
IGF2BP2 also shares sentences with these, for which no sentence is quoted: female infertility (3 papers); gallbladder carcinoma (3); pancreatic adenocarcinoma (3); hypopharyngeal squamous cell carcinoma (2); infertile (2); inflammatory bowel disease (2); lung squamous cell carcinoma (2); rheumatoid arthritis (2); acute megakaryoblastic leukemia (1); acute respiratory distress syndrome (1); allergic rhinitis (1); autoimmune disease (1); B-cell acute lymphoblastic leukemia (1); Barrett esophagus (1); basal cell carcinoma (1); benign tumors (1); bile duct cancer (1); brain injury (1); breast invasive carcinoma (1); chronic myeloid leukaemia (1); Crohn disease (1); cutaneous melanoma (1); diabetic cardiomyopathy (1); Diabetic Foot Ulcers (1); diffuse large B-cell lymphoma (1); dysplasia (1); End-Stage Renal Failure (1); endocervical adenocarcinoma (1); endocrine system disease (1); endometrial adenocarcinoma (1).
A further 34 diseases each share a sentence with IGF2BP2 in 1 paper.